NRON (non-coding repressor of NFAT)
Synonyms: NCRNA00194
Gene: Miscellaneous RNA gene on chromosome 9 (126,408,041 to 126,408,410, reverse strand). Ensembl gene ENSG00000253079.
Homologues: Orthologues: chimpanzee NRON (99% identical), guinea pig NRON (92% identical).
Diseases named in the same sentence as NRON in open-access papers:
NRON is named in the same sentence as 23 diseases in open-access papers, as found by Europe PMC text mining. Sharing a sentence is not in itself a finding about the gene and the disease. The quoted sentences say what the papers report.
HIV-1 infection (4 papers, 2015 to 2023). The type species of lentivirus and the etiologic agent of acquired immunodeficiency syndrome (AIDS). "Both GAS5 and NRON were previously shown to be downregulated during HIV-1 infection, which led to increased viral replication." (PMID 36674541, 2023). "A recent study reported a novel gene, named NRON, which can regulate HIV-1 infection by inducing the degradation of tat protein." (PMID 30996114, 2019). "Previously known lncRNAs 7SK RNA, NEAT1, NRON repress HIV-1 infection, and lncRNAs uc002yug. activates HIV-1 replication and reactivates HIV-1 from latency." (PMID 30788509, 2019). "GAS5 and NRON are known to be downregulated upon HIV-1 infection in cell line experiments." (PMID 36674541, 2023). "NRON mediates the degradation of tat protein to participate in HIV-1 infection." (PMID 30996114, 2019). "We profiled 90 disease-related lncRNAs and found NRON (noncoding repressor of Nuclear Factor of Activated T cells [NFAT]) to be one of several lncRNAs whose expression was significantly altered following HIV-1 infection." (PMID 25728138, 2015). "We also made the novel observation that Vpu, which is expressed late in HIV-1 infection, decreases NFAT activity by increasing NRON levels." (PMID 25728138, 2015).
bladder cancer (3 papers, 2020 to 2023). "The upregulation of NRON in bladder cancer patients was significantly associated with the depth of bladder tumor invasion and poor prognosis." (PMID 32194786, 2020). "In this study, we showed that NRON is upregulated in BC tissues and cell lines, and the upregulation of NRON in bladder cancer patients was significantly associated with the depth of bladder tumor invasion and poor prognosis." (PMID 32194786, 2020). "In the present study, we revealed that the upregulation of NRON in bladder cancer patients was significantly associated with the depth of bladder tumor invasion and poor prognosis." (PMID 32194786, 2020). "A similar pathway by lncRNA NRON occurs to increase bladder cancer metastasis." (PMID 35236381, 2022). "For example, the expression of lncRNAs such as TUC338 and PVT1 can be used as biomarkers for early diagnosis of bladder cancer, while the expression of PCAT6, NRON, GAS6-AS2, SNHG3, lncRNA TP73-AS1, and LINC00641 can predict poor prognosis of bladder cancer." (PMID 37592177, 2023). "Mechanistically, NRON stimulates EZH2 signaling to provide EMT induction and bladder cancer migration." (PMID 35236381, 2022).
triple-negative breast carcinoma (2 papers, 2019 to 2020). An invasive breast carcinoma which is negative for expression of estrogen receptor (ER), progesterone receptor (PR), and human epidermal growth factor receptor 2 (HER2). "NRON was also down-regulated in triple-negative breast cancer (TNBC), and NRON down-regulates lncRNA snaR to inhibit TNBC cell proliferation." (PMID 32194786, 2020). "Interestingly, our study observed the down-regulation of NRON in triple-negative breast cancer (TNBC) tissues compared with paired adjacent healthy tissues." (PMID 30996114, 2019).
AIDS (1 paper, 2021). A syndrome resulting from the acquired deficiency of cellular immunity caused by the human immunodeficiency virus (HIV). "Furthermore, some ncRNAs have emerged as potential therapeutic targets, some of which include lncRNAs NEAT1, NEAT2 and lnr6RNA, 152742 in tuberculosis; MALAT1, HEAL, SAF, lincRNA-p21, NEAT1, GAS5, NRON, LINC00173 in HIV/AIDS; miRNA-146a in malaria." (PMID 34737736, 2021).
bladder tumor (1 paper, 2020). "In this study, we showed that the expression of NRON was increased in BC tissues, and NRON up-regulation was significantly associated with the depth of bladder tumor invasion and poor prognosis in patients with BC." (PMID 32194786, 2020).
breast carcinoma (1 paper, 2021). "The lncRNA NRON can regulate osteoclastogenesis during orthodontic bone resorption, reduce atrial fibrosis by promoting NFATc3 phosphorylation, inhibit breast cancer development via regulating miR-302b/SRSF2 axis." (PMID 34861891, 2021).
gastric cancer (1 paper, 2021). A primary or metastatic malignant neoplasm involving the stomach. "In this study, we explored the expression and biological role of lncRNA NRON in gastric cancer (GC)." (PMID 34659574, 2021).
glioblastoma (1 paper, 2025). The most malignant astrocytic tumor (WHO grade IV). "NRON, known for its role in cancer-related immune responses, including T-cell activation, showed downregulated expression in our study, with the most significant decrease observed in the CPt + SAHA treatment combination, despite the limited literature on its involvement in glioblastoma." (PMID 40004468, 2025).
inflammatory bowel disease (1 paper, 2018). A spectrum of small and large bowel inflammatory diseases of unknown etiology. "LRRK2 can be physically associated with NRON and this protein-RNA complex has been proven to be a NFAT suppressor in many inflammatory diseases such as inflammatory bowel disease, and LRRK2 deficiency can lead to a more serious inflammation response." (PMID 29545945, 2018).
Myocardial fibrosis (1 paper, 2019). "Finally, we investigated the role of NRON in regulating myocardial fibrosis by determining expression of Collagen I and Collagen III." (PMID 31693733, 2019).
cancer (8 papers, 2014 to 2025). A tumor composed of atypical neoplastic, often pleomorphic cells that invade other tissues. "In human disease other than cancer, it has been reported that NRON modulates HIV-1 transcription and replication by increasing NFAT activity." (PMID 32194786, 2020). "The results showed that NRON was significantly down-regulated in TNBC tissues comparing to non-cancer tissues (P<0.05)." (PMID 30996114, 2019). "NRON is likely to have different functions in different cancer cells." (PMID 32194786, 2020). "We therefore conclude that NRON may down-regulate lncRNA snaR to inhibit cancer cell proliferation in TNBC." (PMID 30996114, 2019). "NRON overexpression inhibited cancer cell proliferation and down-regulated snaR." (PMID 30996114, 2019). "LncRNA NRON, a repressor of activated T-cell nuclear factor (NFAT), has been shown to be dysregulated in many cancer types." (PMID 32194786, 2020). "Therefore, it is reasonable to hypothesize that NRON may also participate in cancer biology." (PMID 30996114, 2019). "Therefore, NRON may only interact with pathways involved in cancer cell proliferation." (PMID 30996114, 2019). "The present study reported the down-regulation of NRON in TNBC and its inhibitory effects on cancer cell proliferation." (PMID 30996114, 2019). "Furthermore, several cancer-promoting or tumor-suppressing lncRNAs, such as NEAT1, H19, NRON, LUCAT1, and HOTAIR, can be found not only in malignant cells but also in tumor-specific immune cells." (PMID 36911393, 2023). "The snaR overexpression resulted in promoted cancer cell proliferation but did not significantly affect NRON expression." (PMID 30996114, 2019). "However, our study observed a big overlap of NRON expression levels between TNBC and non-cancer tissues." (PMID 30996114, 2019). "Although no direct evidence to indicate the anti-cancer role of NRON, its repression for NFAT that plays pivotal role in tumorigenesis, cell proliferation, migratory, invasive and drug resistance, suggests a potential tumor suppressive function." (PMID 26378581, 2015). "including two markers first identified in HCC—Kcnq1ot1 (KCNQ1 overlapping transcript 1), a well-characterized tumor suppressor and NRON [noncoding repressor of NFAT (nuclear factor of activated T-cells)] to repress NFAT functions involved in carcinogenesis, cancer cell proliferation and metastasis." (PMID 26378581, 2015). "In addition, snaR overexpression promoted cancer cell proliferation (P<0.05) but did not significantly affect NRON expression, while NRON overexpression inhibited cancer cell proliferation (P<0.05) and down-regulated snaR (P<0.05)." (PMID 30996114, 2019). "We speculated that NRON may indirectly interact with snaR due to the lack of correlation between NRON and snaR in non-cancer tissues." (PMID 30996114, 2019). "Interestingly, our study observed the decreased NRON expression level along with the increase of clinical stages, but NRON overexpression failed to affect cancer cell migration and invasion (only slight inhibitory effect, data not shown)." (PMID 30996114, 2019). "LncRNA NRON overexpression inhibited cancer cell proliferation and down‐regulated lncRNA snaR in TNBC, while snaR overexpression did not significantly affect NRON expression." (PMID 33314471, 2021).
tumor (6 papers, 2015 to 2023). "High expression of NRON was associated with tumor invasion depth." (PMID 33842553, 2021). "Our results provide important clues regarding NRON as an oncogene and promising tumor biomarker for BC." (PMID 32194786, 2020). "Our results suggested that NRON acted as an oncogene and tumor biomarker for BC." (PMID 32194786, 2020). "Thereafter, we also analyzed the expression patterns of NRON, EZH2 and EMT markers in these tumor samples from nude mice." (PMID 32194786, 2020). "We investigated the involvement of NRON in TNBC and found that NRON was down-regulated in TNBC and played an tumor suppressive role in TNBC by down-regulating oncogenic lncRNA snaR." (PMID 30996114, 2019). "NRON is a non-coding repressor of NFAT, and it is a tumor suppressor." (PMID 30189670, 2018). "Only Kcnq1ot1 and NRON were significantly up-regulated in HBV positive compared with viral negative non-tumor tissues." (PMID 26378581, 2015). "This is consistent with our discrepant observations that repressed Kcnq1ot1 and NRON were observed in HBV-related HCC tumor compared with adjacent non-tumor tissues, while up-regulated Kcnq1ot1 and NRON were found in HBV-related HCC compared with viral negative non-tumor tissues." (PMID 26378581, 2015).
infection (3 papers, 2015 to 2021). The state of being infected such as from the introduction of a foreign agent such as serum, vaccine, antigenic substance or organism. "Jurkat or U937 cells were infected with HIV-1 NL4-3 or a Nef-deficient variant, NL4-3ΔNef, and NRON levels were quantified at different times post-infection by qRT-PCR." (PMID 25728138, 2015). "Analogous to this, infection of U937 or Jurkat cells with the NL4-3 and NL4-3ΔVpu viruses showed reduced NRON levels in the absence of Vpu." (PMID 25728138, 2015).
NRON also shares sentences with these, for which no sentence is quoted: hepatocellular carcinoma (1 paper); infarction (1); leishmaniasis (1); leprosy (1); malaria (1); myocardial infarction (1); osteoporosis (1); schizophrenia (1); tuberculosis (1); viral infection (1).